ELF4 (E74 like ETS transcription factor 4)
Description:
Transcriptional activator that binds to DNA sequences containing the consensus 5'-WGGA-3'. Transactivates promoters of the hematopoietic growth factor genes CSF2, IL3, IL8, and of the bovine lysozyme gene. Acts synergistically with RUNX1 to transactivate the IL3 promoter (By similarity). Transactivates the PRF1 promoter in natural killer (NK) cells and CD8+ T cells. Plays a role in the development and function of NK and NK T-cells and in innate immunity. Controls the proliferation and homing of CD8+ T-cells via the Kruppel-like factors KLF4 and KLF2 (By similarity). Can also promote cellular transformation through inhibition of the p16 pathway. Is a transcriptional regulator of inflammation, controlling T-helper 17 (Th17) cells and macrophage inflammatory responses. Required for sustained transcription of anti-inflammatory genes, including IL1RN. Is a negative regulator of pro-inflammatory cytokines expression including IL17A, IL1B, IL6, TNFA and CXCL1. Down-regulates expression of TREM1, a cell surface receptor involved in the amplification of inflammatory responses (By similarity).
Synonyms: ELFR; MEF; AIFBL2
Tractability: PROTAC: ubiquitination databases record sites on it.
Gene: Protein-coding gene on chromosome X (130,063,955 to 130,110,904, reverse strand). Ensembl gene ENSG00000102034.
Subcellular location: Nucleus, PML body
Subcellular location (Human Protein Atlas): Nuclear bodies; Nucleoplasm
Gene Ontology:
Molecular function: DNA-binding transcription activator activity, RNA polymerase II-specific; protein binding; RNA polymerase II cis-regulatory region sequence-specific DNA binding; sequence-specific double-stranded DNA binding; DNA-binding transcription factor activity, RNA polymerase II-specific; DNA-binding transcription factor activity; sequence-specific DNA binding
Biological process: negative regulation of inflammatory response; negative regulation of interleukin-1 beta production; negative regulation of interleukin-6 production; negative regulation of tumor necrosis factor production; positive regulation of DNA-templated transcription; positive regulation of transcription by RNA polymerase II; cell differentiation; natural killer cell proliferation; NK T cell proliferation; regulation of transcription by RNA polymerase II; regulation of DNA-templated transcription
Cellular component: nuclear body; PML body; chromatin; nucleus
Gene-disease validity (ClinGen):
ClinGen rates the evidence that ELF4 causes each of these diseases.
autoinflammatory syndrome, familial, X-linked, Behcet-like 2 (X-linked): Definitive.
Cancer hallmarks: cell replicative immortality (promotes); escaping programmed cell death (suppresses); suppression of growth (promotes); proliferative signalling (promotes)
Homologues: Orthologues: chimpanzee ELF4 (99% identical), macaque ELF4 (99% identical), pig ELF4 (92% identical), guinea pig ELF4 (89% identical), dog ELF4 (89% identical), rabbit ELF4 (86% identical), rat Elf4 (79% identical), mouse Elf4 (78% identical). Paralogues in human: ELF1 (34% identical), ELF2 (29% identical), ERG (13% identical), ELK4 (12% identical), ELK3 (12% identical), FLI1 (12% identical), ERF (12% identical), GABPA (11% identical), ELK1 (11% identical), ETV3 (11% identical), ETS2 (11% identical), ETS1 (11% identical), and 16 more.
Diseases named in the same sentence as ELF4 in open-access papers:
ELF4 is named in the same sentence as 76 diseases in open-access papers, as found by Europe PMC text mining. Sharing a sentence is not in itself a finding about the gene and the disease. The quoted sentences say what the papers report.
glioma (9 papers, 2016 to 2025). A benign or malignant brain and spinal cord tumor that arises from glial cells (astrocytes, oligodendrocytes, ependymal cells). "The present research comprehensively analyzed the association of ELF4 expression with epigenomics, clinical outcomes, tumor immunity, and sensitivity to anti-tumor drugs in glioma." (PMID 39132148, 2024). "Furthermore, we demonstrated the differences in TME reprogramming associated with ELF4 expression in glioma." (PMID 39132148, 2024). "In glioma, high ELF4 expression up-regulates the SRY-box transcription factor 2 (SOX2) expression, enhancing cancer stem cells' features and promoting tumor occurrence." (PMID 40083328, 2025). "ELF4 knockout delayed proliferation and apoptosis of glioblastoma cells and resulted in long-term growth delay and morphological changes in glioma stem cells (GSCs)." (PMID 41300273, 2025). "The representative IHC images demonstrated the ELF4 were upregulated in glioma samples, which was validated by the IHC images in HPA database." (PMID 39132148, 2024). "The key objective of the present research was to comprehensively analyze the prognostic value of ELF4 in glioma." (PMID 39132148, 2024). "Our research displayed that ELF4 was a reliable predictor of an unfavorable prognosis in glioma and correlated with clinicopathological characteristics such as IDH mutation status, 1p19q codeletion, and WHO grade, through a comprehensive analysis." (PMID 39132148, 2024). "Our findings indicated that ELF4 was a promising biomarker to predict the clinical outcomes of glioma." (PMID 39132148, 2024). "Firstly, the DEGs associated with ELF4 subgroups were detected by R package Limma in TCGA, CGGA, and Gravendeel glioma sets." (PMID 39132148, 2024). "In the present research, comprehensive analyses demonstrated that elevated expression of ELF4 in glioma tissues correlates with malignant phenotypes and adverse clinical outcomes." (PMID 39132148, 2024). "In summary, our study performed a comprehensive examination of the possible mechanisms involved in ELF4 dysregulation in glioma and established its adverse effect on clinical outcomes." (PMID 39132148, 2024). "Nevertheless, the precise role of ELF4 in glioma pathology and its impact on clinical outcomes remains to be investigated." (PMID 39132148, 2024). "In the Gravendeel set, ELF4 expression was increased in the aged glioma samples and IDH wildtype samples." (PMID 39132148, 2024). "Based on TCGA data, we found that gliomas with high ELF4 expression displayed elevated levels of both silent and non-silent mutation rates, SNV neoantigens, number of segments, fraction altered as well as aneuploidy score." (PMID 39132148, 2024). "ELF4 is elevated in high grade gliomas, particularly in glioma and neuronal stem cell markers, including CD44, CD36, CD15, CD70, S100A4, and ALDH1A3." (PMID 38539424, 2024). "Nonetheless, more investigation is needed to ascertain the exact ways in which ELF4 influences the development and prognosis of glioma." (PMID 39132148, 2024). "Survival analysis revealed patients with elevated ELF4 expression levels had a higher likelihood of experiencing unfavorable outcomes which was confirmed in both TCGA and Gravendeel glioma cohorts." (PMID 39132148, 2024). "The scRNA-seq glioma sets demonstrated that ELF4 was involved in the infiltrates of immune cells and particularly highly expressed in TAMMs, including monocytes, macrophages, and microglia." (PMID 39132148, 2024). "In conclusion, lncPVT1 facilitates stemness and TMZ resistance through regulating miR-365/ELF4/SOX2 signal axis in glioma." (PMID 35965522, 2022). "ELF4 has been reported to be highly expressed in glioma and can upregulate SOX2 expression to promote stemness." (PMID 35965522, 2022). "ELF4 knockout mice have impaired neurosphere formation and slow glioma growth, and ELF4 may promote the growth of gliomas by upregulating Sox2." (PMID 41300273, 2025).
glioma (continued). "Knockdown of ELF4 reduced the cell viability and migration capacity of glioma cells in vitro." (PMID 39132148, 2024). "Our glioma-specific drug sensitivity analysis has been conducted further in this section and demonstrated that overexpressed ELF4 might elevate the response to veliparib, motesanib, and EHT 1864 in gliomas." (PMID 39132148, 2024). "The correlation analysis of tumor immunity calculated by the ESTIMATE method with ELF4 expression demonstrated that ELF4 could influence TME reprogramming in glioma." (PMID 39132148, 2024). "Our research discovered a higher frequency of IDH mutation in the low ELF4 expression subgroup in LGG samples, which might contribute to the advantageous outcomes of gliomas in the low ELF4 subgroup." (PMID 39132148, 2024). "As indicated by AUC values, ELF4 expression demonstrated a strong and accurate ability to predict glioma OS at 1 year (CGGA: 0.670; TCGA: 0.789; Gravendeel: 0.714), at 3 years (CGGA: 0.711; TCGA: 0.773; Gravendeel: 0.756), and at 5 years (CGGA: 0.737; TCGA: 0.725; Gravendeel: 0.689)." (PMID 39132148, 2024). "Using CGGA set, ELF4 expression level was increased with glioma grade (p<0.001)." (PMID 39132148, 2024). "Multivariate Cox regression analysis determined that ELF4 expression could serve as a reliable predictor of glioma outcomes." (PMID 39132148, 2024). "Considering that ELF4 is a transcription factor, similar to its function in gliomas, there might be some target genes that ELF4 transcriptionally regulates in ESCC." (PMID 37674363, 2023). "Currently, the relevant role and molecular mechanisms of ELF4 in cancer development remain unclear; ELF4 exerts different functions in different tumors, and ELF4 has tumor-promoting effects in ovarian cancer and glioma." (PMID 41300273, 2025). "Therefore, ELF4 hypomethylation might be the main factor to induce its dysregulated expression in gliomas." (PMID 39132148, 2024). "In the present research, ELF4 expression demonstrated a strong correlation with expression PD-1 and TIM-3 in glioma, which further illustrated that the overexpressed ELF4 could lead to the formation of the suppressive TME in glioma, and decreased anti-tumor immunity." (PMID 39132148, 2024). "RT-qPCR demonstrated that ELF4 was effectively knockdown by si-ELF4-1 in U87MG and U251 glioma cells, compared with the mRNA expression level of ELF4 in the si-control (si-CTL) group." (PMID 39132148, 2024). "It has also been reported that long non‐coding RNA PVT1 induces up‐regulation of SOX2 expression through the miR‐365/ELF4 axis, thereby promoting the maintenance of stemness and TMZ resistance in glioma cells." (PMID 36184801, 2022). "Using microarray datasets from patients with different grades of glioma, we have analyzed the expression profiles of various ETS genes, and have identified ETV1, ELK3, ETV4, ELF4, and ETV6 as novel biomarkers for the identification of different glioma grades." (PMID 33671331, 2021). "In addition, lncRNA PVT1 sponges miR-365 to up-regulate ELF4, which in turn serves as an upstream regulator of SOX2, thereby facilitating the stemness features and temozolomide resistance of glioma." (PMID 40083328, 2025). "We assessed the expression of ELF4 mRNA in both glioma and non-tumor tissues and explored its correlation with glioma patient prognosis and clinical characteristics." (PMID 39132148, 2024). "In the TCGA set, The ELF4 expression was remarkably elevated in IDH wildtype glioma samples, 1p19q non-codeletion glioma samples, and the aged glioma samples (age≥ 65 years)." (PMID 39132148, 2024). "Using data from the GEPIA database, we identified that ELF4 was elevated in glioma, in comparison with ELF4 mRNA expression in the non-tumor brain tissues and validated the finding in Gravendeel set (p<0.001)." (PMID 39132148, 2024).
glioma (continued). "In glioma, recent research demonstrates that the long non-coding RNA PVT1 oncogene enhances stemness and resistance to temozolomide (TMZ) in glioma through the miR-365/ELF4/SRY-Box Transcription Factor 2 (SOX2) pathway." (PMID 39132148, 2024). "Furthermore, both ELF4 and ETV6 expressions are downregulated at grade 2 glioma, but upregulated at increasing levels in grades 3 and 4, indicating that these genes can also be utilized as additional molecular determinants to distinguish glioma grades." (PMID 33671331, 2021). "The correlation of IC50 values of the drugs/ compounds with ELF4 expression in the three glioma datasets were calculated and the Motesanib (AMG 706), EHT 1864, Veliparib (ABT-888), CCT007093 were filtered out based on the correlation analysis of compounds with ELF4 |cor|>0.30 and p<0.05." (PMID 39132148, 2024). "In the CGGA set, The ELF4 expression was remarkably increased in IDH wildtype glioma samples, and 1p19q non-codeletion glioma samples." (PMID 39132148, 2024).
acute myeloid leukaemia (5 papers, 2020 to 2025). "The earliest evidence that ELF4 is involved in cancer comes from its fusion protein with AML1 in acute myeloid leukemia." (PMID 41300273, 2025). "The aberrant interaction of ELF4 with the onco-fusion protein acute myeloid leukaemia (AML1)/ETO is an example of the involvement of ELF4 in cancer biology." (PMID 37674363, 2023). "The formation of the fusion protein of ELF4 and ERG-1 has also been found in acute myeloid leukemia, but the specific effect remains unclear." (PMID 41300273, 2025).
glioblastoma (5 papers, 2023 to 2025). The most malignant astrocytic tumor (WHO grade IV). "Researchers performed high-throughput functional siRNA screens in glioblastoma cells and identified ELF4 as a major contributor to the oncogenic phenotype." (PMID 41300273, 2025). "In both human and mouse glioblastoma, ELF4 is highly expressed and patients with lower expression of ELF4 tend to have longer survival times." (PMID 40083328, 2025). "In glioblastoma, high ELF4 expression promotes proliferation and stemness, reducing patient survival." (PMID 41287970, 2025). "Additionally, ELF4 is critical to glioblastoma cell identity through the control of genes in two dependent pathways: RTK signaling (SRC, PTK2B, and TNK2) and lipid dynamics (LRP1, APOE, ABCA7, PLA2G6, and PITPNM2)." (PMID 41300273, 2025). "For instance, ELF4 is highly expressed in human glioblastomas (GBM), promotes GBM cell proliferation and stemness, and influences the survival periods of GBM patients." (PMID 36923538, 2023). "In addition, PVT1 regulates E74-like factor 4 (ELF4) expression by competitively binding to miR-365 and controls the stemness of GSCs via the miR-365/ELF4/SOX2 axis Thus, PVT1 may serve as a potential therapeutic target and prognostic indicator in glioblastoma." (PMID 39015773, 2024).
inflammatory bowel disease (5 papers, 2022 to 2025). A spectrum of small and large bowel inflammatory diseases of unknown etiology. "A recent report indicates that mutations of ELF4 in patients causes human autoinflammatory disease with inflammatory bowel disease (IBD) characteristics." (PMID 35563234, 2022). "ELF4 is a mediator of anti-inflammatory responses and protects against mucosal disease in human inflammatory bowel disease." (PMID 36209117, 2022). "In addition, this study provides a new approach for the clinical application of small-molecule drugs targeting ELF4 to treat inflammatory bowel diseases." (PMID 38022496, 2023). "Thus, ELF4 attenuates inflammation and protects against mucosal diseases, which provides a potential targeted therapeutic strategy for human inflammatory diseases including inflammatory bowel disease." (PMID 40083328, 2025). "The research provides crucial insights into the role of the transcription factor ELF4 in mitigating inflammatory bowel disease (IBD), expanding our understanding of the molecular mechanisms involved in the progression and possible treatments for IBD." (PMID 38022496, 2023).
colorectal cancer (4 papers, 2021 to 2025). A primary or metastatic malignant neoplasm that affects the colon or rectum. "In colorectal cancer, increased ELF4 expression is positively associated with distant metastasis, advanced American Joint Committee on Cancer (AJCC) stages, and poor patient outcomes." (PMID 40083328, 2025). "In colorectal cancer, ELF4 expression is significantly positively associated with proliferating T (Tprolif) cells, endothelial cells, and epithelial cells." (PMID 40083328, 2025). "Aberrant ELF4 expression is implicated in cancer cell proliferation, stemness, and therapy resistance across multiple malignancies, including leukemia, ovarian cancer, glioma, cervical cancer, hepatocellular carcinoma, and colorectal cancer." (PMID 41287970, 2025). "In some tumors, including colorectal cancer, ELF4 expression is elevated compared with normal tissues and is associated with poor prognosis." (PMID 40083328, 2025). "Recent research shows FGF19 induces ELF4 in colorectal cancer, driving metastasis via ELF4‐mediated FGFR4 and Src kinase signaling." (PMID 41287970, 2025). "ELF4 is an independent biomarker for predicting poor prognosis in colorectal cancer." (PMID 40083328, 2025). "Thus, FGF19/ELF4/FGFR4 generates a positive feedback loop to enhance colorectal cancer cell metastasis." (PMID 40083328, 2025). "In colorectal cancer, overexpression of ELF4 transactivates fibroblast growth factor receptor 4 (FGFR4) and non-receptor tyrosine kinase (SRC) to facilitate the metastasis of colorectal cancer." (PMID 40083328, 2025).
gastric cancer (4 papers, 2023 to 2025). A primary or metastatic malignant neoplasm involving the stomach. "For example, Tumor-derived exosomes carrying LINC01091 facilitated gastric cancer (GC) progression through mediating miRNA-128-3p/ELF4/CDX2 axis." (PMID 39425009, 2024). "In gastric cancer, exosomal lncRNA LINC01091 enhances the expression of ELF4 by binding to miR-128-3p." (PMID 40083328, 2025). "In turn, ELF4 transactivates the expression of caudal type homeobox 2 (CDX2), thereby boosting growth, migration, invasion, and metastasis of gastric cancer." (PMID 40083328, 2025). "LINC01091 can coordinate the microRNA-128-3p/ELF4/CDX2 axis and thus promote gastric cancer growth and metastasis by way of exosomes on one hand and can act as hub lncRNA in DNA methylation-related prognostic signatures of prostate cancer." (PMID 37822927, 2023).
lung adenocarcinoma (4 papers, 2021 to 2025). A carcinoma that arises from the lung and is characterized by the presence of malignant glandular epithelial cells. "In lung adenocarcinoma, plasma cell tumors, multiple myeloma, and colon cancer, ELF4 exerts a tumor suppressor function." (PMID 41300273, 2025). "Although many studies have described ELF4 as an oncogenic protein, ELF4 can act as a tumor suppressor in some tumors, including lung adenocarcinoma and prostate tumors." (PMID 37674363, 2023). "Additionally, ELF4 expression is inhibited in various epithelial cancer cells, and ELF4 overexpression in the lung adenocarcinoma cell line A549 can inhibit the growth of cancer cells in nude mice." (PMID 41300273, 2025).
colitis (3 papers, 2022 to 2024). Inflammation of the colon. "Bioinformatics showed that LPS-induced colitis animals have reduced ELF4 expression in their colon tissue." (PMID 38022496, 2023). "Our recent work has shown that ELF4 knockout mice develop normally but are sensitive to dextran sulfate sodium salt (DSS) induced colitis, and azoxymethane (AOM) combined with DSS induced colitis-associated cancer (CAC)." (PMID 35563234, 2022). "Taken together, we can conclude that dysfunction of ELF4 leads to colitis in both induced mouse models and human patients." (PMID 35563234, 2022). "In vivo tests confirmed reduced ELF4 expression in mice with LPS-induced colitis." (PMID 38022496, 2023). "Our previous study has shown that ELF4 transcriptionally regulates multiple DNA damage repair machinery components, and that ELF4 deficiency leads to cell damage and mice sensitive to DSS-induced colitis." (PMID 35563234, 2022). "Dysfunction of E74-like ETS transcription factor 4 (ELF4) leads to colitis." (PMID 35563234, 2022).
endometrial cancer (3 papers, 2023 to 2025). Primary or metastatic malignant neoplasm involving the endometrium (mucous membrane that lines the endometrial cavity). "In endometrial cancer, ELF4 acts as the effector of TRIB3 to drive tumorigenesis." (PMID 36923538, 2023).